APOA1 (apolipoprotein A1)
Diseases named in the same sentence as APOA1 in open-access papers (continued):
Sharing a sentence is not in itself a finding about the gene and the disease.
Sepsis (continued). "Therefore, an apoA-1 mimetic or a CETP inhibitor could be a novel therapy for sepsis in the future." (PMID 36671490, 2023). "Although an increase in SAA levels in HDL is linked to HDL degradation, consistent with our previous reports, we did not observe any significant changes in plasma HDL-cholesterol or apoA1 levels between WT and SAA-TKO mice in sepsis." (PMID 38139330, 2023). "This displacement of apoA-1 by SAA is evident in HDL of patients with CHD, end-stage renal disease (ESRD), and sepsis, all of which display increased levels of SAA and decreased levels of apoA-1 in HDL in comparison to healthy controls." (PMID 33260660, 2020). "In summary, the delta decrease ratio was the most appropriate measurement to detect gram- sepsis compared with the individual variation in the serum HDL-C and apoA1 levels." (PMID 27462492, 2016). "In addition, ATP-binding cassette transporters, transforming lipid-poor apolipoprotein A1 into mature HDL, and lecithin-cholesterol acyltransferase (LCAT), converting free cholesterol to cholesterol esters, are also affected during sepsis." (PMID 38015312, 2023). "Furthermore, LPS stimulation downregulated apolipoprotein A1 (APOA1) expression, which is involved in the efflux of cholesterol from the cells, suggesting that sepsis can lead to increased cellular cholesterol levels." (PMID 34439987, 2021). "LDL-C, TC, apoA-1, and apoB were significantly decreased in sepsis nonsurvivors and decreased apoA-1 predicted sepsis-related 30-day mortality." (PMID 34087197, 2021). "Similarly, in our sepsis cohort, we were able to show that the SOFA score as a marker for disease severity correlated significantly with ApoA1 levels, and ApoA1 levels were reduced in septic patients." (PMID 33195328, 2020). "During acute inflammation such as sepsis, HDL particles may become inflammatory (serum amyloid A may displace ApoA1)." (PMID 32290632, 2020). "From the analysis of the lipids levels of the sepsis patients with different gram-stained bacteria at admission, we found that compared with the patients with gram+ sepsis, HDL-C (p < 0.001) and apoA1 (p = 0.008) were significantly reduced in the patients with gram− sepsis." (PMID 27462492, 2016). "ApoA1 levels were lowest in patients with severe sepsis with shock and also in the SIRS group without infections, and both groups were highly significantly different from the control group (P < 0.001)." (PMID 22512779, 2012). "The aim was to determine the plasma concentrations of apoM during sepsis and systemic inflammatory response syndrome (SIRS) and correlate them to levels of apolipoprotein A-I (apoA1), apolipoprotein B (apoB), HDL-, and low-density lipoprotein (LDL)-cholesterol." (PMID 22512779, 2012). "ApoA1 was not different between the gram+ and gram− sepsis patients after 24 h." (PMID 27462492, 2016). "Data in dogs are limited, but ApoA-1 is considered as a potential biomarker of canine systemic inflammatory response syndrome (SIRS) and sepsis acting as a negative acute-phase protein (APP)." (PMID 41437958, 2025). "There were no apparent differences in the levels of apolipoprotein A1 (apoA1) in the plasma of WT and SAA-TKO mice following sepsis as indicated by western blots." (PMID 38139330, 2023). "Apolipoprotein-A1 (Apo-A1) acts as a negative acute phase protein (APP) during inflammatory states, and has a potential prognostic value in people and dogs with sepsis." (PMID 36937011, 2023).
Stroke (66 papers, 2012 to 2026). Sudden impairment of blood flow to a part of the brain due to occlusion or rupture of an artery to the brain. "Increased levels of anti-ApoA1 IgG antibodies have been shown to be associated with higher risk of major cardiovascular events including stroke." (PMID 35054033, 2022). "Several studies have indicated an correlation of the ApoB/ApoA1 ratio and the risk of stroke, intracranial and extracranial carotid stenosis." (PMID 32017458, 2020). "Anti-ApoA-1 IgG serum levels have been found to predict worse post-stroke outcomes and HCV is associated with increased cerebrovascular morbidity and mortality." (PMID 29423541, 2018). "There are still no data available to conclusively explain whether the decreased ApoA1 level belongs to the pathophysiology of the acute phase of stroke or is only associated with an increased risk of stroke in this group." (PMID 35054033, 2022). "The ethnic difference in the impact of the ApoB/ApoA1 ratio on stroke risk may be related to genetics or metabolism." (PMID 34082746, 2021). "Available evidence shows that ApoB-100 and ApoA-1 and, more importantly, the ApoB-100/ApoA-1 ratio could predict cardiovascular heart disease and stroke risk more accurately than conventional lipid measurements; a value <1 is recommended." (PMID 25084280, 2014). "Genetic polymorphisms (e.g., APOA1 rs670, APOA5 rs662799) further complicate disease risk, showing population-specific associations with stroke and neurodegeneration." (PMID 40869228, 2025). "Subgroup analyses indicated that the predictive value of neutrophil to apolipoprotein A1 ratio differed across stroke subtypes." (PMID 38550307, 2024). "Genetically predicted levels of ApoB/ApoA1 and M-HDL-C were more strongly associated with CHD than HF or stroke." (PMID 38724583, 2024). "The purpose of this study was to clarify the prognostic value of ApoB/ApoA1 for stroke recurrence and alleviate future cerebrovascular disease." (PMID 38274879, 2023). "Only on the seventh day after the stroke differences were found regarding Bf, ApoA1, Fn, fetuin A, TrpRS and ficolin-2." (PMID 35054033, 2022). "Previous study found that the level of APOA1 was decreased in patients with post-stroke depression than in HCs." (PMID 35372107, 2022). "Jong‐Ho Park also suggested that a higher ApoB/ApoA1 ratio is a predictor of intracranial atherosclerotic stenosis in Asian patients with stroke (Park, Hong, Lee, Kim, & Song, 2013)." (PMID 32017458, 2020). "Available evidence shows that ApoB-100 encloses all atherogenic lipoproteins and is a reliable predictor, together with the ApoB/ApoA1 ratio, of CVD and stroke risk." (PMID 28704936, 2017). "On the 7th day after the stroke, differences were found between the study group and the control group (group B vs. C) regarding complement factor B (Bf), apolipoprotein A-I (ApoA1), fetuin A, fibronectin (Fn), cytoplasmic tryptophanyl-tRNA synthetase (TrpRS) and ficolin-2." (PMID 35054033, 2022). "Moreover, in the INTERSTROKE study (n = 13,447 patients with stroke and 13,472 controls from 32 countries), 26.8% of strokes were due to an increased apoB/ApoA1 ratio." (PMID 35076490, 2021). "As there is a study suggesting an association between Aβ and fatigue, a possible mechanism could be considered where blood apolipoprotein A1 levels affect the Aβ toxicity inside the brain, leading to differential complaints of fatigue in post-stroke patients." (PMID 34942944, 2021). "Serum samples of 94 patients in the ischemic stroke group and 37 patients in the non-stroke group were analyzed for the levels of total APOA1-UP, low density lipoprotein cholesterol (LDL-C), triglycerides (TG), high-density lipoprotein cholesterol (HDL-C), and total cholesterol (TC)." (PMID 27043525, 2016). "ApoB/ApoA1 was associated with MI and stroke, but not HF in the observational analysis." (PMID 38724583, 2024).
Stroke (continued). "A multivariable logistic regression model was developed in the full cohort using six predictors: National Institutes of Health Stroke Scale (NIHSS) score, age, admission systolic blood pressure, uric acid, apolipoprotein A1, and neutrophil percentage." (PMID 42111063, 2026). "Median ratio of total APOA1-UP/LRP was 2.14 (interquartile range, 0.40) in the non-stroke group and 1.32 (0.44) in the ischemic stroke group (p < 0.0001)." (PMID 27043525, 2016). "The median serum APOA1-UP/LRP was 1.49 (interquartile range (IQR), 0.77) in total samples, 2.14 (IQR, 0.40) in the control group, and 1.32 (IQR, 0.44) in the stroke group, with a p value of <0.0001." (PMID 27043525, 2016). "Univariate Cox regression revealed that history of stroke, creatinine (Cr), left ventricular ejection fraction(LVEF), TG, HDL, TC/HDL, ApoB, ApoA1/ApoB, Fg, pulmonary artery pressure (PAP), high GS group, TVD, and PCSK6 rs1531817 genotypes were associated with the occurrence of MACEs." (PMID 39039525, 2024). "For stroke, only several M-HDL traits and ApoB/ApoA1 were found significant." (PMID 38724583, 2024). "ApoB, apoA-1, and the apoB/apoA-1 ratio were analysed in relation to MACEs (non-fatal MI, stroke, and cardiovascular [CV] mortality), yielding 22,473 events." (PMID 34851955, 2021). "However, there is a lack of research into the correlation between ApoB/ApoA1 and stroke recurrence after the first episode." (PMID 38274879, 2023). "However, some authors suggested that the usefulness of ApoA1 appears to be of little use in the early diagnosis of stroke as its concentrations do not change significantly in the first 28 days following an ischemic event." (PMID 35054033, 2022).
COVID-19 (60 papers, 2020 to 2025). A disease caused by infection with severe acute respiratory syndrome coronavirus 2. "Several studies have reported that lower levels of HDL-C and ApoA1 are associated with more severe COVID-19 outcomes, including thromboinflammation and endothelial dysfunction." (PMID 40565828, 2025). "This study is the first to explore the association of high-density lipoprotein and apolipoprotein A1 with COVID-19 outcomes using US population data." (PMID 37372137, 2023). "There is a causal association for subjects with low ApoA1 and, 10 years later, low levels were correlated with the risk of COVID-19." (PMID 35327501, 2022). "The present results were limited by the absence of adjustments on confounding factors associated with serum ApoA1 levels, such as dietary folate, physical exercise, and vitamin C and alcohol intake both before and during COVID-19." (PMID 35327501, 2022). "The introduced central proteins of the S-COVID-19 interaction network, particularly APOA1, can be considered as diagnostic and therapeutic targets related to the coronavirus disease after being approved with complementary studies." (PMID 33244380, 2020). "The current study demonstrated that higher levels of HDL and apoA1 could reduce the risk of SARS-CoV-2 infection as well as the risks of developing severe cases of COVID-19 and AKI." (PMID 37372137, 2023). "Similarly, smoking was associated with a lower incidence of infection in both HDL and apoA1 groups though it was a risk factor for both severe COVID-19 and AKI in one group." (PMID 37372137, 2023). "Moreover, patients with the highest tertile of HDL-C and apoA-1 displayed the lowest risk for severe COVID-19." (PMID 33344516, 2020). "This study analyzed data from the National COVID Cohort Collaborative, the largest US COVID-19 database, to determine if an association exists between COVID-19 and blood levels of high-density lipoprotein, and high-density lipoprotein’s main protein component, apolipoprotein A1." (PMID 37372137, 2023). "Researches had indicated that ApoA1 levels can serve as a predictor of COVID-19 severity, with adequate levels potentially acting as a protective factor against severe outcomes." (PMID 40809523, 2025). "A bioinformatics study found that the more severe the disease, the lower level of ApoA1 in COVID-19." (PMID 40809523, 2025). "This examination not only aims to enhance our understanding of the role of ApoA1 as prognostic marker but also seeks to contribute to the development of innovative therapeutic approaches for managing COVID-19." (PMID 40809523, 2025). "The largest COVID-19 United States-based database analysis results suggested that higher ApoA1 protect against SARS-CoV-2 infection." (PMID 40809523, 2025). "The most influential variables across the top 10 models included telomere length, HbA1c, vitamin D3, waist circumference, ApoA1, C peptide, ApoB, COVID-19 severity, duration of T2D, IL-6, cholesterol, BMI, and age." (PMID 40950970, 2025). "APOA1 has anti-viral activity and was previously reported as a strong predictive factor of COVID-19 severity when detected at low levels in COVID-19 patients." (PMID 38672194, 2024). "Lowered concentrations of cholesterol-rich lipoproteins in COVID-19 correlated with the severity of the underlying disease, and HDL-cholesterol, its major apolipoprotein A-1 (ApoA-1) and total cholesterol levels were predictive of mortality." (PMID 39408818, 2024). "While patients with COVID-19 experience a cytokine storm; TC, HDLc, ApoA1, albumin, total protein levels decrease as well as CD16+ T, CD3+ T, and CD8+ T cell counts." (PMID 38753890, 2024). "According to the literature, APOA1 is considered one of the key proteins involved in the pathophysiology of COVID-19 serving as an important diagnosis and therapeutic marker for this infection." (PMID 38510452, 2024).
COVID-19 (continued). "Both high HDL and apoA1 values reduced the odds of severe COVID-19 (OR = 0.99 with p < 0.001 for HDL, and OR = 0.99 with p = 0.075 for apoA1 values), although apoA1 was statistically significant only at 10%." (PMID 37372137, 2023). "The main findings of this study is that COVID-19 induces a humoral response against the c-terminal part apoA-1 in IRD, corroborating and extending previous observations in immunocompetent populations." (PMID 37234173, 2023). "The current study is the first national-level study that leveraged the N3C database to investigate the roles of HDL and apoA1 on outcomes of COVID-19 in the US population." (PMID 37372137, 2023). "Of note was that for six markers (CRP, ferritin, IL-6, IP-10, SAA1/A2, and S100A12) higher values were detected in COVID-19 sera whereas for ApoA1, significantly lower levels were detected in the COVID-19 group (p<0 · 0001)." (PMID 36590898, 2023). "While the protective roles of HDL and apoA1 have been well established for the infection and the severity of COVID-19, our study is the first to show the role of HDL in preventing AKI." (PMID 37372137, 2023). "Higher values of HDL and apoA1 also reduced the odds of severe COVID-19 by 1%, although the impact of apoA1 was statistically significant only at 0.5 < p ≤ 0.1, likely due to the small sample size." (PMID 37372137, 2023). "Despite the current limitations in the N3C data, this study is the first to investigate the roles of HDL and apoA1 on the outcomes of COVID-19 using the US population data." (PMID 37372137, 2023). "Recently published plasma proteomic studies of COVID-19, in contrast, report finding decreased levels of APOA1." (PMID 36967377, 2023). "The deficiency in apolipoproteins levels in COVID-19 compared to normal human plasma (NHP) and ICU-ARDS patients was most pronounced for APOA1, APOA2, APOA4, APOC3 and APOE." (PMID 37031181, 2023). "Pathways depicting cholesterol, HDL and LDL metabolism (WP430, WP5109, WP4522, WP3601) are also among the top 10 pathways that have reduced activity in COVID-19 patients with significant reductions in APOA1, APOA2, APOC2, APOC3, APOB protein abundance." (PMID 36189295, 2022). "During COVID-19, T2DM was associated with a significant and very early decrease in ApoA1 in patients younger than 20 years of age compared with non-T2DM patients, both in men and women." (PMID 35327501, 2022). "Before COVID-19, T2DM was associated with a significant and very early decrease in ApoA1 in patients younger than 20 years of age compared with non-T2DM patients, in both in men and women." (PMID 35327501, 2022). "We used the “NAFLD-Serum” cohort to confirm the previous findings: that before and during COVID-19, T2DM was associated with a decrease in ApoA1 compared with non-T2DM patients, in both in men and women." (PMID 35327501, 2022). "Recently, a panel of five proteins with downregulated expression, namely, albumin (ALB), apolipoprotein A1 (APOA1), apolipoprotein C1 (APOC1), gelsolin (GSN), and transferrin (TF), was identified as a core signature associated with the severity of COVID-19." (PMID 34471261, 2021). "Our results also highlighted the predictive value of decreased HDL/apoA-1 levels on admission to in-hospital death in COVID-19 patients." (PMID 33344516, 2020). "Lipid metabolism disorders, characterized by low HDL-C and apoA-1 levels, were found in severely ill COVID-19 patients." (PMID 33344516, 2020). "The results specify that up-regulation of C3 and down-regulation of APOA1 in urine play a role in the stiffness in respiration and, accordingly, the severity of COVID-19." (PMID 33244380, 2020). "Based on multivariate analyses, decreased apoA-1 and HDL-C levels were independently associated with COVID-19 severity after adjusting for established indicators of severity, such as age, low albumin, and increased D-dimer, CRP, and IL-6 levels." (PMID 33344516, 2020).